DGAT1 (diacylglycerol O-acyltransferase 1)
Diseases named in the same sentence as DGAT1 in open-access papers (continued):
Sharing a sentence is not in itself a finding about the gene and the disease.
heart failure (5 papers, 2018 to 2025). Inability of the heart to pump blood at an adequate rate to meet tissue metabolic requirements. "Half of the cardiac DGAT1 knockout mice died by nine months of age, with an increase in heart failure markers and cardiac dysfunction." (PMID 37233656, 2023). "Cardiomyocyte‐specific ablation of Dgat1 also induced severe lipotoxic heart failure, mediated by DAG and ceramide." (PMID 35411952, 2022). "Humans with severe heart failure have a marked reduction in FA oxidation and DGAT1 mRNA levels in the heart and accumulate DAG and ceramides." (PMID 30081476, 2018). "Indeed, cardiomyocyte-specific DGAT1 knockout mice exhibit severe increases in ceramide and diacylglycerol, as well as cardiomyopathy, linking aberrant metabolism of these lipids to diabetes and heart failure." (PMID 39456198, 2024). "However, humans with severe heart failure have notably reduced levels of DGAT1 mRNA in the heart." (PMID 39456198, 2024). "In accordance, cardiomyocyte-specific DGAT1 knockout mice also accumulate toxic lipids, mostly DAG and ceramides, in the heart and have increased mortality due to heart failure." (PMID 30081476, 2018).
hyperlipidemia (5 papers, 2014 to 2023). "The pharmacological inhibition of DGAT-1 reduced hepatic lipid accumulation and serum triglyceride concentrations in rodent models of postprandial hyperlipidemia." (PMID 36882750, 2023). "This is consistent with the previous observations on the suppression by other DGAT1 inhibitors of postprandial hyperlipidemia and the delayed fat absorption in DGAT1 null mice." (PMID 25405858, 2014).
neuroblastoma (5 papers, 2022 to 2024). Neuroblastoma (NB) is the most common solid, extracranial childhood tumor. "The most significantly altered levels of lipid metabolite were TGs, which resulted from the change in DGAT1 expresssion in human neuroblastoma cells." (PMID 35888761, 2022). "NEST expression increased the mRNA levels of diacylglycerol acyltransferase 1 (DGAT1), but not DGAT2, the key enzymes of TG biosynthesis in neuroblastoma cells incubated with or without OA." (PMID 35888761, 2022).
Protein-losing enteropathy (5 papers, 2017 to 2026). Abnormal loss of protein from the digestive tract related to excessive leakage of plasma proteins into the lumen of the gastrointestinal tract. "A strong suspicion of DGAT1 deficiency should be held for newborns with protein-losing enteropathy, growth retardation, and unexplained diarrhea and vomiting." (PMID 39171021, 2024). "Biallelic loss-of-function mutations in human DGAT1 result in severe congenital diarrhea and protein-losing enteropathy." (PMID 28373485, 2017). "Our findings add to the growing recognition of DGAT1 deficiency as a cause of congenital diarrhea with protein-losing enteropathy and indicate that DGAT1 mutations result in a spectrum of diseases." (PMID 28373485, 2017). "Loss-of-function mutations in DGAT1 result in protein-losing enteropathy (PLE), characterized by early-onset, non-bloody watery diarrhea, with patients often presenting with severe dehydration, malnutrition, and growth retardation, particularly during infancy." (PMID 40868152, 2025).
viral infection (5 papers, 2020 to 2025). "In the present study, we found that neuroinvasive virus infection could enhance the LD formation while targeting DGAT1/2 to reduce LD production could suppress neuroinvasive virus infection by increasing the release of cellular AA." (PMID 38490434, 2024). "Similar mechanisms involving DGAT-1 and LD have been reported to other viral infections." (PMID 33326472, 2020).
alopecia (4 papers, 2015 to 2024). Hair loss usually from the scalp. "Comparative studies on the impact of diacylglycerol O-acyltransferase 1 (DGAT1) on mouse and dog alopecia suggest that mice may be an especially sensitive species." (PMID 38628581, 2024). "Importantly, negative aspects of systemic Dgat1 deficiency such as alopecia and mammary gland atrophy are absent in iDgat1−/− mice (unpublished observations) and upon pharmacological inhibition of Dgat1." (PMID 32882484, 2020).
Diarrhea (4 papers, 2020 to 2025). Abnormally increased frequency (usually defined as three or more) loose or watery bowel movements a day. "Herein, we report a female patient who had delayed-onset chronic diarrhoea with a compound heterozygous DGAT1 mutation, which, to our knowledge, has not been previously reported." (PMID 33261563, 2020).
liver cancer (4 papers, 2016 to 2024). An epithelial or non-epithelial malignant neoplasm that arises from the liver. "vs PANC-1 CTR: 0.2 ± 0.0 vs 1.0 ± 0.0; P < 0.0001) and liver cancer cells (Hepa-1c1c7) (Hepa-1c1c7 DGAT1 in." (PMID 30816200, 2019). "Because these cell lines are originated from liver cancers, our results may not precisely reflect the actual effects of DGAT1 silencing in normal hepatocytes." (PMID 26493024, 2016).
mastitis (4 papers, 2009 to 2025). Inflammation of breast tissue during lactation or postpartum due to an obstructed duct or infection. "For example, the expression and RNA splicing of DGAT1 from multiple tissues regulated milk production, mastitis, gestation length, temperament, and stature." (PMID 40688095, 2025). "DGAT1 expression and splicing affected milk production, mastitis (MAS, average correlation with milk production traits r ̄milk = −0.01), gestation length (Gl, r ̄milk = −0.03), temperament (Temp, r ̄milk = −0.04), and stature (Stat, r ̄milk = 0.09)." (PMID 40688095, 2025).
diarrheal disorder (3 papers, 2013 to 2025). "Although histopathological findings in DGAT1-related diarrhea remain less well characterized compared to other hereditary diarrheal disorders, abnormalities in lipid metabolism and mucosal structural alterations have been implicated." (PMID 40868152, 2025).
glioma (3 papers, 2021 to 2022). A benign or malignant brain and spinal cord tumor that arises from glial cells (astrocytes, oligodendrocytes, ependymal cells). "The knockdown of DGAT1 increases glioma ceramide levels in vitro, and DGAT1 inhibition with the drug T863 reduces the volume of LDs in the GBM cells." (PMID 36012521, 2022). "The clear correlation between DGAT1 inhibition and sphingolipid production in gliomas makes this a promising target for continued therapeutic investigation." (PMID 36012521, 2022). "And the inhibition of DGAT1 in PA-treated cells would increase C16 ceramide which induced tumor growth while C18 ceramide did not11,55, inferring that inhibition of PA-induced LDs may lead to a worse outcome in treating gliomas." (PMID 33795756, 2021). "Therefore, targeting DGAT1 may be a potential therapeutic approach for glioma treatment." (PMID 35935861, 2022).
hepatitis C (3 papers, 2013 to 2023). "For example, ATGL inhibitors could offer the possibility of treating cachexia, or DGAT1 inhibitors could be tested as a means to prevent hepatitis C infection." (PMID 23740690, 2013).
Hypercholesterolemia (3 papers, 2016 to 2021). An increased concentration of cholesterol in the blood. "Taken together, our results demonstrate that in a murine model of atherosclerosis, Dgat1 deficiency exclusively in enterocytes is sufficient to prevent diet-induced hypercholesterolemia without major effects on fasting TG homeostasis." (PMID 32882484, 2020). "Targeting intestinal DGAT1 may represent a novel approach for treating hypercholesterolemia." (PMID 27344248, 2016).
liver disease (3 papers, 2016 to 2025). "It aligns with a clinical trial where DGAT1 levels fell as liver disease progressed from MASH to cirrhosis." (PMID 38474754, 2024). "To determine the clinical relevance of DGAT1 silencing, we first analysed several data sets of various human liver diseases in the GEO, a public gene expression profile database." (PMID 26493024, 2016). "A recent study validated a set of five differentially expressed and co-upregulated genes (DEGs) (DGAT1, AMOT, PDE11A, TYMS, and TMEM98) that were elevated in patients with atrial fibrillation, liver disease, and atrial fibrillation associated with liver disease compared to healthy controls." (PMID 40141794, 2025).
lung carcinoma (3 papers, 2020 to 2022). "Meta-analysis of 6 hub genes of lung cancer was performed by ONCOMINE databases, and showed that UGT1A6 and DGAT1 were upregulated, while HPGDS and LPL were downregulated." (PMID 33050938, 2020). "In agreement with this speculation, the pharmacological depletion of LDs by DGAT1 and DGAT2 inhibitor treatment significantly slows down cell growth and proliferation of lung cancer cells, especially those with higher LD contents, such as A549 and H460." (PMID 36293388, 2022).
pancreatic cancer (3 papers, 2019 to 2024). "To determine whether DGAT1 was a common enzyme utilized by other tumor cell types, we used the same DGAT1 inhibitor treatment regimen and found a similar effect in reducing the proliferative rate in both pancreatic cancer cells (PANC-1) (PANC-1 DGAT1 in." (PMID 30816200, 2019). "Overexpression of HILPDA, but not DGAT1/2, is associated with shorter overall survival in pancreatic cancer patients, suggesting that additional roles of HILPDA, other than regulating triacylglyceride (TAG) synthesis, may influence the outcome of pancreatic cancer patients." (PMID 34078402, 2021).
astrocytoma (2 papers, 2024). "The expression level of DGAT1 and LD content in GBM tumor tissues from patients with grade I-IV astrocytomas (n = 62) was detected using tissue microarray and immunofluorescence." (PMID 38500157, 2024). "Results showed that grade IV GBM tissues contained the highest levels of DGAT1 compared with anaplastic astrocytoma (AA, grade III), astrocytoma II (A2), and pilocytic astrocytoma (PA, grade I)." (PMID 38500157, 2024).
atherosclerosis (2 papers, 2016 to 2020). A disease characterized by the build-up of fatty material and calcium deposition in the arterial wall resulting in partial or complete occlusion of the arterial lumen. "We have previously shown that ApoE-/-Dgat1-/- mice are protected from developing atherosclerosis in association with reduced foam cell formation." (PMID 27223895, 2016). "On one hand, global DGAT1 deficiency protects against atherosclerosis." (PMID 27223895, 2016). "Thus, whereas global DGAT1 deficiency may protect against both plaque development and plaque inflammation in atherosclerosis-prone mice, DGAT1 deficiency specifically in the myeloid compartment might paradoxically worsen atherosclerosis." (PMID 27223895, 2016). "In addition to its role in controlling TG homeostasis, DGAT1 may also play a role in atherosclerosis, a disease usually linked to dysregulated cholesterol homeostasis." (PMID 27223895, 2016). "Our results demonstrate that iDgat1−/−ApoE−/− mice phenocopy systemic Dgat1 disruption with reduction in the total cholesterol burden, resulting in substantial attenuation of atherosclerosis in iDgat1−/−ApoE−/− mice." (PMID 32882484, 2020). "Our data support the possibility that DGAT1 plays a dual role in atherosclerosis." (PMID 27223895, 2016). "However, he-matopoietic Dgat1 deficiency lacked beneficial effects on atherosclerosis." (PMID 32882484, 2020). "ApoE−/− mice globally lacking Dgat1 activity are protected from atherosclerosis by at least two mechanisms: (i) reduced macrophage foam cell formation and increased cholesterol efflux, and (ii) reduced uptake of dietary cholesterol." (PMID 32882484, 2020). "Moreover, Dgat1−/− mice are characterized by reduced hepatic steatosis, increased transintestinal cholesterol excretion (TICE), extended life span, and reduced atherosclerosis." (PMID 32882484, 2020).
cardiomyopathy (2 papers, 2022 to 2025). A disease of the heart muscle or myocardium proper. "Additionally, the overexpression of DGAT1 in the heart resulted in the development of cardiomyopathy, an increase in cardiac fibrosis, and a decrease in heart mitochondrial biogenesis over time." (PMID 36230994, 2022).
enteropathy (2 papers, 2019 to 2024). "Despite initial investigations ruling out common causes like celiac disease, genetic analysis confirmed DGAT1 enteropathy." (PMID 39171021, 2024). "The enteropathy is the result of an inborn error of lipid metabolism caused by a variant in the DGAT1 gene." (PMID 31057599, 2019).
experimental autoimmune encephalomyelitis (2 papers, 2022 to 2024). An autoimmune demyelinating disease of the central nervous system that is produced experimentally in animals by the injection of homogenized brain or spinal cord in Freund's adjuvant. "DGAT1 participated in the polarization of T cells into retinol-dependent Treg cell formation, which attenuated experimental autoimmune encephalomyelitis." (PMID 39043892, 2024). "DGAT1 induced Treg formation to attenuate experimental autoimmune encephalomyelitis." (PMID 36457997, 2022).
Failure to thrive (2 papers, 2024 to 2025). Failure to thrive (FTT) refers to a child whose physical growth is substantially below the norm. "This study summarized a cohort with (likely) pathogenic genomic variants in DGAT1, all presenting with a phenotype of vomiting, congenital diarrhea, failure to thrive, and malnutrition." (PMID 40868152, 2025). "Here, we present a case of a one-year-old boy with persistent watery diarrhea, vomiting, and failure to thrive, ultimately diagnosed with DGAT1 deficiency through genetic testing." (PMID 39171021, 2024).
Glucose intolerance (2 papers, 2006 to 2019). Glucose intolerance (GI) can be defined as dysglycemia that comprises both prediabetes and diabetes. "In contrast, mice lacking DGAT1 in adipocytes have normal TG storage on a chow diet but moderately decreased body fat accompanied by glucose intolerance when challenged with a high-fat diet." (PMID 30936184, 2019).
Hyperinsulinemia (2 papers, 2012). An increased concentration of insulin in the blood. "RGS5 deficiency would likely involve enhanced Gαi-mediated signal pathway and be in charge of increased lipogenesis (mediated by DGAT1, DGAT2 and GPAT1) and decreased lipolysis (mediated by HSL and ATGL), under the conditions of hyperinsulinemia and high FFA, which can induce adipocyte hypertrophy." (PMID 22272317, 2012).
liver cirrhosis (2 papers, 2016 to 2022). "We assumed that the decreased DGAT1 expression in cirrhotic liver might have an association with increased proliferative activity in regenerative hepatocytes, and demonstrated DGAT1 down‐regulation in patients with liver cirrhosis without fatty degeneration." (PMID 26493024, 2016). "The complete and long-term silencing of DGAT1 decreased E-cadherin and integrin β1, an adhesion molecule that contributes to the cell-extracellular matrix or cell-substrate adhesion, similar to the process of liver cirrhosis without fatty degeneration." (PMID 40396035, 2022). "Collectively, these results indicate that down‐regulation of DGAT1 and integrin β1 may be involved in the progression of liver cirrhosis without fatty degeneration." (PMID 26493024, 2016).
liver fibrosis (2 papers, 2022 to 2024). "Extensive research corroborates that DGAT1 exacerbates lipid storage in hepatocytes, and drugs targeting this protein can reduce liver fibrosis and inflammation in a murine NASH model." (PMID 38549670, 2024). "Treatment with Dgat1-ASO inhibits the activation of HSCs in mice and rats, increases the expression of LRAT, promotes the accumulation of RE in the liver, and alleviates liver fibrosis." (PMID 36569303, 2022).
lung adenocarcinoma (2 papers, 2024 to 2025). A carcinoma that arises from the lung and is characterized by the presence of malignant glandular epithelial cells. "However, in lung adenocarcinoma, the mRNA level of DGAT1 was upregulated compared to normal tissues, and patients with high DGAT1 expression (n = 357) had a better survival rate compared to those with low DGAT1." (PMID 38500157, 2024).
malnutrition (2 papers, 2017 to 2025). Inadequate nutrition resulting from poor diet, malabsorption, or abnormal nutrient distribution. "In conclusion, in a rare case of a child presenting with watery stools, decreased muscle tone, and severe malnutrition, a missense and intronic site mutation in DGAT1 was identified through routine WES." (PMID 40868152, 2025). "Children with DGAT1 deficiency can be very ill, and one death was reported from complications of malnutrition." (PMID 28373485, 2017).
ovarian tumor (2 papers, 2022 to 2025). "In fact, the levels of DGAT1 are positively associated with ovarian tumor growth; the larger the tumor, the more DGAT1 will be produced, likely supporting the storage of ever-increasing amounts of lipid." (PMID 35634242, 2022).
prostate tumor (2 papers, 2019 to 2021). "In contrast, there was a significant loss of PEDF in the prostate tumor cells and a stepwise gain in DGAT1 protein expression was observed when LNCaP was compared to the more aggressive PC-3 cell line." (PMID 30816200, 2019). "Another group demonstrated that inhibition of DGAT1 reduced prostate tumor growth, indicated that DGAT1 could support tumor growth both directly and indirectly." (PMID 33750350, 2021). "In this study, we postulated that the higher rate of lipid flux in prostate tumors cells is maintained, in part, by modulating the crosstalk between the key enzyme in TAG lipogenesis, DGAT1, and the lipolysis regulating proteins ATGL and PEDF." (PMID 30816200, 2019).
psoriasis (2 papers, 2024 to 2026). An autoimmune condition characterized by red, well-delineated plaques with silvery scales that are usually on the extensor surfaces and scalp. "Unexpectedly, while DGAT1 expression was elevated in human psoriatic lesions and in a murine psoriasis model, DGAT1 loss reduced keratinocyte proliferation in this inflammatory condition." (PMID 42268475, 2026). "Using a mouse model of psoriasis, we show that DGAT1-deficiency reduces energy-demanding neutrophil infiltration to the site of inflammation, but this inhibition is not caused by decreased glycolysis and reduced ATP production by neutrophils lacking DGAT1." (PMID 39043892, 2024). "Our findings establish DGAT1 as a context-dependent regulator of keratinocyte proliferation, promoting growth in homeostasis while restraining it in psoriasis." (PMID 42268475, 2026). "In this study we use the mouse model of psoriasis to elucidate the influence of DGAT1 on neutrophil activity in chronic inflammation." (PMID 39043892, 2024). "Flow cytometry and immunohistochemistry analysis of psoriasis-like skin demonstrated a markedly lower number of these cells in Dgat1KO mice in comparison to WT littermates, suggesting an impaired DGAT1-mediated neutrophil infiltration into psoriatic skin." (PMID 39043892, 2024).
stomach adenocarcinoma (2 papers, 2020 to 2021). "Surprisingly, we found the elevated expression of DGAT1 in tumor infiltrating macrophage also showed negative correlation with poor overall survival in stomach adenocarcinoma patients." (PMID 33750350, 2021). "DGAT1 gene expression was increased in both SRCCs and STADs (TCGA cohort) than non-malignant pairs, suggesting its increased expression in stomach adenocarcinoma universally." (PMID 32732980, 2020). "SGS data for 33 pairs of stomach adenocarcinomas (STADs) and adjacent non-malignant tissues from The Cancer Genome Atlas (TCGA) cohort also demonstrated higher expression of DGAT1 in cancers (Mann–Whitney U test, p = 0.002)." (PMID 32732980, 2020).
acute myeloid leukemia (1 paper, 2024). Acute myeloid leukemia (AML) is a group of neoplasms arising from precursor cells committed to the myeloid cell-line differentiation. "CDCA suppressed acute myeloid leukemia (AML) progression by promoting both lipid droplets (LD) accumulation and lipid peroxidation via ROS/p38 MAPK/DGAT1 pathway." (PMID 38444942, 2024).